ETDC (embryonic testis differentiation homolog C)
Gene: Protein-coding gene on chromosome X (135,271,717 to 135,309,803, forward strand). Ensembl gene ENSG00000283644.
Homologues: Orthologues: chimpanzee ETDC (98% identical). Paralogues in human: ETDA (78% identical), ETDB (78% identical).